PRSS38 (serine protease 38)
Synonyms: MPN2
Tractability: Antibody: UniProt places it where antibodies can reach, with high confidence; UniProt predicts a signal peptide or a membrane-spanning region; its Gene Ontology location is reachable by antibodies, with medium confidence.
Gene: Protein-coding gene on chromosome 1 (227,815,675 to 227,846,470, forward strand). Ensembl gene ENSG00000185888.
Subcellular location: Secreted
Gene Ontology:
Molecular function: serine-type endopeptidase activity
Biological process: proteolysis
Cellular component: extracellular region
Genetic constraint (gnomAD): Loss-of-function variants: 20 observed, 26.27 expected, observed/expected ratio (o/e) 0.76, 90% interval 0.54 to 1.11. The upper end of that interval is the gene's LOEUF score, 1.11, which puts it in group 4 of 6, group 1 being the genes least tolerant of losing a copy. Missense variants: 413 observed, 429.49 expected, observed/expected ratio (o/e) 0.96, 90% interval 0.89 to 1.04. Synonymous variants: 172 observed, 173.79 expected, observed/expected ratio (o/e) 0.99, 90% interval 0.87 to 1.12.
Homologues: Orthologues: chimpanzee PRSS38 (98% identical), macaque PRSS38 (92% identical), dog PRSS38 (66% identical), rat Prss38 (60% identical), guinea pig PRSS38 (58% identical), mouse Prss38 (57% identical), zebrafish si:dkey-238d18.3 (29% identical), zebrafish ctrl (28% identical), zebrafish zgc:171592 (27% identical). Paralogues in human: CTRL (30% identical).
Diseases named in the same sentence as PRSS38 in open-access papers:
PRSS38 is named in the same sentence as 1 disease in open-access papers, as found by Europe PMC text mining. Sharing a sentence is not in itself a finding about the gene and the disease. The quoted sentences say what the papers report.
male infertility (1 paper, 2025). The inability of the male to effect fertilization of an ovum after a specified period of unprotected intercourse. "This study provides, for the first time, an integrated analysis of PRSS38 in human and mouse sperm, contributing to our understanding of mammalian fertilization and male infertility." (PMID 41373827, 2025).